CD44 (CD44 molecule (IN blood group))
Diseases named in the same sentence as CD44 in open-access papers (continued):
Sharing a sentence is not in itself a finding about the gene and the disease.
cancer (continued). "CD133, CD90, CD44, and EPCAM have been shown to be markers for cancer stem cells in HCC patients." (PMID 22187659, 2011). "EpCAM, CD44, CD166, CD133 are the cancer stem cell marker for colorectal cancer." (PMID 22082307, 2011). "In addition, we found major populations of cells that express vimentin with CD44 and only a minor subset that express these molecules with CD133, a potential marker on cancer stem cells." (PMID 24212937, 2011). "The table shows that none of the cancer cell types listed was positive for both CD44 and CD133, markers most often cited as associated with cancer stem cells." (PMID 21605402, 2011). "As hormone influence plays an important role in prostate cytodifferentiation, lack of androgen may also lead to increased expression of progenitor cell markers (CD133, CD44, CD117, ABCG2) in cancer cells." (PMID 21605402, 2011). "CD44/CD24, CD29, CD133, CD200 are the cancer stem cell marker for breast cancer." (PMID 22082307, 2011). "CD44 and CD133 expression detected in non-cancer could be due to basal or other cell types as total prostate RNA was used as non-cancer in that analysis." (PMID 21605402, 2011). "CD44 and vimentin are upregulated during epithelial-mesenchymal transition (EMT) of cancer cells." (PMID 22216242, 2011). "Additional proof of HuR involvement with other known cancer genes, such as CD44 and GATA-3, may represent novel insights into the mechanisms of regulation of these cancer targets." (PMID 20370918, 2010). "It has been suggested that cell expression of CD44/24 is not fixed and that cancer is organized stochastically, rather than hierarchically, as the SC model suggests." (PMID 20406437, 2010). "We did, however, not observe increased transcript expression of the cancer stem cell markers CD44, CD133 and the epithelial cell adhesion molecule EpCAM." (PMID 19529782, 2009). "However, in contrast to CD44, only a small portion of CD24+ cells were positive in HNSCC cancer cells in our study." (PMID 19602232, 2009). "This suggests that the CD44+CD24− cells are the clonogenic, tumorigenic cells contained within the LNCaP cell line and that they give rise to the multiple cell types, thereby satisfying the conventional criteria of a cancer stem cell." (PMID 18268494, 2008). "We found that CD44+/CD24-/ESA+ cells exhibit properties of self-renewal in vitro, form tumors from very few cells, divide slowly, and are selectively resistant to chemotherapy, all of which are hallmarks of cancer stem cells." (PMID 18366788, 2008). "These tumorigenic cells have been serially generated in new tumors containing additional CD44+ CD24-/low lineage tumorigenic cells as well as the phenotypically mixed population of non-tumorigenic cancer cells." (PMID 19014671, 2008). "There have been no previous studies implicating CD44+24-/low population as cancer stem cells in mouse models." (PMID 18394172, 2008). "Besides, all the three cell lines were negative for CD34 antigen but they evidenced equal strong positivity for CD29, CD44 and CD90, mesenchymal and cancer stem cells markers." (PMID 18941626, 2008). "Expression of CD44 was shown for all investigated carcinoma cell lines, but not in healthy mouse lung tissue, as determined by western blot analysis." (PMID 19002182, 2008). "As shown by others and in the present study, CD44 expression on the cell surface may define a mechanism for MMP-9 activation and cancer cell migration." (PMID 17343740, 2007). "We further hypothesized that if uPAR-positive cells represent drug-resistant and clonogenic population in SCLC, they may express CD44 and MDR1 (ABCB1) genes, which are involved in development of cancer stem cell phenotype and multi-drug resistance." (PMID 17327908, 2007). "Note that all luminal cell types contain disproportionately higher levels of CD44-/CD24+ cells, and this population may contain cancer progenitor cells corresponding to luminal type of tumors." (PMID 17062128, 2006).
cancer (continued). "Furthermore, bioinformatic analysis of miR‐34a targets in various cancers identifies numerous target genes such as Jagged 1 (JAG1), CD44, SRY (sex determining region Y)‐box 4 (SOX4), Notch homolog 2 (NOTCH2), Matrix metallopeptidase 9 (MMP9), Interleukin 6 (IL‐6), and SMAD family member 4 (SMAD4)." (PMID 40336533, 2025). "Given the importance of establishing the memory feature in cancer immunotherapy that provides long-term treatment benefits, we examined the percentage of effector memory CD4+ (CD3+CD4+CD44+CD62L- cells) and CD8+ T cells (CD3+CD8+CD44+CD62L- cells) in splenocytes of treated mice." (PMID 40585984, 2025). "Our study revealed increased expression of c-Myc together with high expression of the mesenchymal markers VIM (Vimentin), FN1 (Fibronectin), ZEB2 (SIP-1), FOXC2, SNAIL1 (Snail), SNAIL2 (Slug), and TWIST and the cancer stem-like cell marker CD44 in cells and tumors lacking MCPIP1 RNase activity." (PMID 39815326, 2025). "In cancer zone A, cancer cells primarily communicated through the COLLAGEN pathway via ligand–receptor interactions, including Col1a1-(Itga9+Itgb1), Col1a1-Cd44, Col1a2-(Itga9+Itgb1), and Col1a2-Cd44, with Col1a2-(Itga9+Itgb1)/Cd44 showing the strongest interaction strength." (PMID 40723284, 2025). "However, the role of soluble CD44 in cancer has not been comprehensively discussed in recent reviews." (PMID 41440277, 2025). "Moreover, in most cases, the development of new HA-based delivery systems is directed towards the treatment of solid tumors, while hematological malignancies often remain without due attention, despite the high expression of CD44 on blood cancer cells." (PMID 39851489, 2025). "We observed a steady trend towards smaller migration areas in spheroids with blocked CD44 compared with control, resulting in statistically smaller migration areas by 92 h confirming that CD44 binding to HMW-HA was an important component of U87 cancer cell migration behaviour." (PMID 40881990, 2025). "Also, some studies have shown that CD44 and STAT3 cooperate with each other in cancer promotion." (PMID 38385088, 2024). "In addition to CD44, Nanog Homeobox (Nanog), SRY (Sex Determining Region Y)-Box 2 (SOX2), and Octamer-Binding Transcription Factor 4 (Oct4) play crucial roles in maintaining cancer stemness progression and the poor prognoses in cancer patients." (PMID 38612715, 2024). "Notably, we identified several key ligand-receptor pairs in TNChigh cancer cells and immune cells, including NECTIN2-TIGIT, MIF-(CD74+CD44), MDK-NCL, LAMB3-CD44, COL1A2-CD44, COL1A1-CD44, CD99-CD99, APP-CD74, and GZMB-PARD3 were identified in TNChigh cancer cells and immune cells." (PMID 38711034, 2024). "Interestingly, unlike the role of CD44 in other cancer, it was found to display the opposite effect." (PMID 38783892, 2024). "Putative copy number alterations analyzed by GISTIC (Genomic Identification of Significant Targets in Cancer) through cBioPortal indicate that the increase in copy number of the CD44 gene could not explain the observed mRNA upregulation." (PMID 38790166, 2024). "Ligand LGALS9 with its receptors (CD44, CD47, and HAVCR2) showed that the inflammatory meta program also interacted with immune cells, implying that it is a cysteine/galactose binding protein that can compromise the functions of NK and T cell to facilitate cancer cell immune escape." (PMID 38944814, 2024). "However, to date, research on CD44 in the liver has primarily focused on cancer, and not much is known about the role of CD44 in other disease conditions." (PMID 38731968, 2024). "In fact, it has been reported that in cancer cells, the GCX functions as a mechanosensory organ that senses interstitial flow, and affects the expression of matrix metalloproteinase‐1 (MMP‐1), MMP‐2, CD44, and α3 integrin which regulate cell motility and metastasis induced by interstitial flow." (PMID 39300946, 2024).
cancer (continued). "The first identified BCSCs were a subset of cells with CD44+CD24−/low phenotype, which could efficiently form tumors in NOD/SCID mice, whereas tens of thousands of CD44−/CD24+ cancer cells could not." (PMID 38254782, 2024). "Additionally, transfer of CD44 from the cancer cell-derived exosomes to HPMC induced the secretion of matrix metalloproteinase-9 (MMP-9) that dispersed the mesothelial barrier and promoted cancer invasion." (PMID 38796525, 2024). "Thus, the mechanism of TSG-6-mediated myeloid suppression and other CD44 expressing non-immune cells in cancer warrants further investigation." (PMID 38987547, 2024). "CAR T cells targeting CD44s or other CD44v expressing cancer cells require further study, for the reason that highly customized CAR T treatments could focus on the differences of CD44 isoforms expressing in cancer cells to improve their specificity and off‐target effect." (PMID 38783892, 2024). "Moreover, analysis of The Cancer Genome Atlas (TCGA) database revealed positive correlations between PA28γ and CD44 mRNA expression, suggesting a potential role for PA28γ in facilitating CD4+ T‐cell differentiation into Th1 cells via the CCL5‐CD44 pathway." (PMID 38721005, 2024). "In order to further characterize the effect of EIF4G2 protein depletion on cancer outcome, and to understand why EIF4G2KD cells are more resistant to therapies, we examined the prevalence of aggressive sub-populations within the control and EIF4G2KD cells by probing for CD133 (PROM1) and CD44." (PMID 38388710, 2024). "Therefore, the co-expression of CD44 & CD133 has been extensively utilized for the isolation and identification of cancer stem cells in a variety of malignant tumors, including but not limited to colorectal cancer, non-small cell lung cancer, ovarian cancer, prostate cancer, and gallbladder cancer." (PMID 38706601, 2024). "Indeed, CD44 is a marker for CSCs in lung, breast, gastric, liver, CRC and AML cancers." (PMID 38612911, 2024). "CD44, a nonkinase single span transmembrane glycoprotein, is a major cell surface receptor for many other extracellular matrix components as well as classic markers of cancer stem cells and immune cells." (PMID 38783892, 2024). "Thus, interaction of osteopontin with cell surface receptors, integrins, and/or CD44 activates JNK, Ras/Raf/MEK/ERK, PI3K/AKT, JAK/STAT, NF-κB, and TIAM1/Rac1 signaling pathways, leading to enhancement of various malignant properties of cancer cells." (PMID 37239056, 2023). "Interestingly, the total level of CD44 in plasma is not significantly different between cancer patients and controls." (PMID 36746966, 2023). "Similarly, LE-LE cancer cells could signal through adhesive ligand-receptor pairs LAMB3-ITGA6_ITGB4 and LAMB3-ITGA6_ITGB1, and inflammatory ligand-receptor pairs MIF-CD74_CD44." (PMID 37596273, 2023). "The slow-release feature of the LDH@aPD-1@CC patch could long-termly maintain a high proportion of memory CD8+ T cells (both Tem+ and Tcm+) in the SLN, especially CD8+ T cells with antigen-specific immune memory (CD44+H-2Ld SPSYVYHQF pentamer+), fighting against cancer resurgence." (PMID 37130873, 2023). "The intracellular, extracellular, and transmembrane domains of CD44 have the ability to bind to various ligands, including hyaluronic acid, collagen, osteopontin (OPN), integrin, and matrix metalloproteinases (MMPs) indicating the pivotal role of this protein in controlling cancer cell fate." (PMID 37491225, 2023). "Of note, CD44 hyperactivation has been reported in many cancers, and binding of CD44 with hyaluronan ligand results in oncogenic activation of signaling pathways which endorse induction of cell proliferation, migration, survival, EMT, and adaptive cancer plasticity." (PMID 37190316, 2023).
cancer (continued). "CD133 expression was present in a subpopulation of cancer cells from 1.1% to 18.0% with a median value of 6.5%; CD44 from 36.0% to 97.0% (median value 80.0%); and cells with CD24 expression consist of 0.0% to 16.0% (median value 7.0%) of the whole population of isolated cancer cells." (PMID 37958844, 2023). "Also, the neutralization assay results showed that mouse polyclonal antibodies were directly cytotoxic on human cancer cells (CD44+) about 70%, but did not affect human normal cells (CD44−)." (PMID 36759786, 2023). "This suggests that the HA/CD44 signalling pathway, rather than CD44 as a molecule, could be a promising target in resistant cancers." (PMID 37958796, 2023). "Also, OCT4, Sox2, Nanog, CD44 and CD133 are generally known as cancer stem-like cell markers." (PMID 36632615, 2023). "OPN roles in cancer progression can also be mediated by the integration of multiple signals, in which OPN could act as a scaffold on multiple cell receptors, including ICOSL, CD44, and several integrins." (PMID 36769264, 2023). "To evaluate the kinetics of cancer stemness changes during the osteogenic and adipogenic inductions, we examined the relative gene expression of the OCT4, SOX2, and NANOG markers in the CD44+ cells at the beginning (0 days), and after 7, 14, and 21 days of differentiation." (PMID 36902135, 2023). "Interestingly, SNAI1-KO cells presented higher stem cell frequency and underwent a switch in the expression of cancer stemness signaling genes, with significant upregulation of epithelial KIT, ALDH1A1 and SOX2, and analogous downregulation of mesenchymal CD44 and SOX9." (PMID 36171192, 2022). "In this context, CD44 has been shown to be active on cancer cells and not in normal cells." (PMID 35211123, 2022). "Thus, we speculated that a decrease in the expression of CD44 in GBM cells would reduce migration and the invasion of cancer cells by modulating β-catenin." (PMID 36231019, 2022). "CD44, a non-kinase glycoprotein, is ubiquitously expressed on various types of cells including cancer stem cells (CSCs) and has been widely studied in recent years in cancer onset and aggressiveness." (PMID 35680853, 2022). "Combined with the increased sensitivity of the high-risk group to ferroptosis caused by the high expression of BID and TAZ, we speculated that the overexpression of CD44 may play a role in antagonizing TAZ and BID, thereby making cancer cells resistant to lipid peroxidation-mediated ferroptosis." (PMID 35155251, 2022). "In the case of CD44, the NCT01358903 trial analyzed the safety and antitumoral activity of the humanized monoclonal antibody RG7356 (also known as RO5429083) designed against CD44 in cancer patients harboring CD44-expressing solid tumors who experienced disease progression on standard therapy." (PMID 35326607, 2022). "However, our results indicate that CD44 neither changes upon cancer progression nor in NED patients during the follow-up." (PMID 35269524, 2022). "CD44 (CD44 molecule) is a non-kinase transmembrane glycoprotein which is overexpressed in multiple cell types, as well as in cancer stem cells, and with a known role in the development and progression of cancer." (PMID 35719390, 2022). "Although our current results suggest that CD44 is a novel PTX3 receptor and that the PTX3/CD44 complex does indeed play a vital role in the promotion of metastasis/invasion and stemness of cancer cells, we cannot rule out other potent PTX3 receptors and their involvement in tumourigenesis." (PMID 35090088, 2022). "The aim of this study was to identify molecular gene signatures, responsible for cancer initiation, progression, resistances and to treatment, metastasis, and also evaluate the potency of our novel compounds SJ10 as potential target for CCNB1/CDC42/MAPK7/CD44 oncogenic signatures." (PMID 35008426, 2022).
cancer (continued). "The CD24+/CD44+ cells with high COL11A1 expression may undergo EMT.COL11A1 is absent in normal pancreatic tissues, which may be a crucial factor for distinguishing between cancer initiation and development." (PMID 35327583, 2022). "Moreover, co-culture of CD44-expressing CAFs and Lewis lung carcinoma (LLC) cells enhances the chemoresistance of LLC cells against 5-FU treatment by upregulating the expression of multidrug resistance protein 1 (MDR1) in cancer cells." (PMID 35884382, 2022). "Notably, these 2 clusters did not express any stemness related genes and were defined as CD44- cancer cells." (PMID 36451812, 2022). "HA/CD44 interactions activate many signaling pathways of protein kinases, cytoskeletal changes, as well as intracellular pathways including Ras, MAPK, and phosphoinositide 3-kinases (PI3K) that contribute to cancer cell division, proliferation, invasion, and angiogenesis, as well as metabolic shift." (PMID 35456670, 2022). "In addition to their functions in cancer progression, CD9 and CD44 are differentially expressed by specific lymph node stromal cell populations and can both suppress podoplanin-dependent contractility and contribute toward lymph node expansion during adaptive immune activation." (PMID 35163233, 2022). "For instance, even though previous research showed that HA has an equivalent cancer cell cytotoxicity to anti-CD44 antibodies, CD44 does not serve as the only receptor for HA and it may not be a specific biomarker for PCa cells." (PMID 33557143, 2021). "There is no doubt that a deeper understanding of the interaction between CD44 and EGFR in cancer progression will provide better approaches to cancer treatment, and that combined EGFR/CD44 targeting may be the future direction in the treatment of some types of cancer." (PMID 33981532, 2021). "Furthermore, the researchers only examined the expression of CD44 cancer stem cells without examining CD44 activity." (PMID 34804499, 2021). "However, the process by which CD44 proteins lose their stemness properties and, consequently, adult stem cells shift to cancer stem cells, is very fragile and has not yet been clearly explained." (PMID 34830890, 2021). "In addition, the downregulation of SPN also induces an increase in the stemness properties of the cells, such as the expression of some cancer stem cell markers (NANOG, OCT4, SOX2, and KLF4) and enrichment in CD44+/CD24- cells, cancer-initiating cells in breast tumors with stem cell properties." (PMID 34066428, 2021). "We further quantified the score of the angiogenesis pathway in CD44+ TAMs from each cancer subtype and observed significantly increased activity in CD44+ TAMs from EPN and AEP compared with that in CD44+ TAMs from SE, suggesting the stronger pro-tumorigenic properties of CD44+ TAMs in EPN and AEP." (PMID 34824203, 2021). "After DDM treatment, the expression levels of HA, CD44, and FR-α were markedly reduced in MCF-7 cells + DDM by 64.6%, 54.6%, and 55.9%, respectively, and in MDA-MB-231 cells + DDM by 43.7%, 53.8%, and 60.4%, respectively, when compared with DDM-free cancer cells." (PMID 34771733, 2021). "As some cancer cells overexpress CD44 receptors capable of interacting with HA and TME is highly abundant in hyaluronidase (HAase), this platform could target CD44-overexpressed tumors and achieve the HAase-mediated release of DC to the cytoplasm to inhibit Glut1." (PMID 34041494, 2021). "We also used CD44 non expressing T47D cell line as a negative control and H1299 cell line as a positive control for HA binding as in our recently published study of targeting CD44 expressing cancer cells." (PMID 34257584, 2021). "HA, a major ECM component of the PC TME, and CD44 interactions elicit diverse signals that regulate CSC self-renewal, maintenance, and MDR in head and neck and breast cancers; however, the role of HA-CD44 binding in the context of chemoresistance in PCSCs remains unclear." (PMID 34453639, 2021).